SLC2A4 (solute carrier family 2 member 4)
Diseases named in the same sentence as SLC2A4 in open-access papers (continued):
Sharing a sentence is not in itself a finding about the gene and the disease.
Hypercholesterolemia (5 papers, 2020 to 2025). An increased concentration of cholesterol in the blood. "Similar effects of fatty acids on Slc2a4 gene expression in adipose tissue could be observed in rats, where treatment with atorvastatin, a drug applied for hypercholesterolemia, restored Slc2a4 gene expression by lowering serum cholesterol and triglycerides." (PMID 37047391, 2023).
Cachexia (4 papers, 2017 to 2024). Severe weight loss, wasting of muscle, loss of appetite, and general debility related to a chronic disease. "Very much in contrast to the situation in cachectic patients, an inflammation outside a cachexia setting has been described to display an initial downregulation of SLC2A4." (PMID 38337428, 2024).
glioma (4 papers, 2024 to 2025). A benign or malignant brain and spinal cord tumor that arises from glial cells (astrocytes, oligodendrocytes, ependymal cells). "Our data demonstrate that pediatric gliomas when compared to adult gliomas have enriched levels of glucose and increased levels of SLC2A4, the transcript that encodes GLUT4." (PMID 40087788, 2025). "Our transcriptional analysis demonstrates that SLC2A4, which encodes the insulin-stimulated glucose transporter GLUT4, is among the most highly enriched transcripts in pediatric gliomas compared to adult, while other GLUT transporters are not significantly different." (PMID 40087788, 2025). "Differences in glucose utilization in pediatric gliomas may be facilitated through overexpression of SLC2A4, which encodes the insulin-stimulated glucose transporter GLUT4." (PMID 40087788, 2025).
prostate carcinoma (4 papers, 2019 to 2025). A carcinoma that arises from epithelial cells of the prostate gland. "D- and G-induced reduction in GLUT4 expression has already been suggested, also after 24 h of treatment with high doses of D and G; however, that study was performed in androgen-sensitive prostate cancer cells (LNCaP-R) and did not investigate Slc2a4 gene expression." (PMID 41150805, 2025).
hyperthyroidism (3 papers, 2022 to 2024). Overactivity of the thyroid gland resulting in overproduction of thyroid hormone and increased metabolic rate. "As a link to increased energy demands with hyperthyroidism, we checked the expression of Slc2a1, Slc2a3 and Slc2a4 encoding for class I glucose transporters GLUT1, GLUT3 and GLUT4, respectively, that facilitate glucose transport across the cell membrane." (PMID 38719881, 2024). "In this study, we observed increased expression of Slc2a4 in osteoblasts with hyperthyroidism in vitro indicating possibly elevated glucose uptake due to higher energy demands in thyroid hormone-stimulated osteoblasts, an effect that was blocked in Bmpr1a-deficient cells." (PMID 38719881, 2024).
Arthritis (2 papers, 2021 to 2025). Inflammation of a joint. "Initially, we observed a reduction in SLC2A4 expression in patients with arthritis, which was potentially linked to the dysregulation of AAM signaling pathways." (PMID 40726988, 2025).
breast invasive carcinoma (2 papers, 2021). "In the Curtis dataset, SLC2A3 mRNA expression was observed 2.665-fold decrease in invasive lobular breast carcinoma samples, while SLC2A4 downregulation was found in invasive breast carcinoma samples with a fold change of 5.226 from TCGA Breast dataset." (PMID 34488531, 2021). "The results showed that the expression level of SLC2A1 were higher in breast invasive carcinoma than in pairing normal tissues, and the expression levels of SLC2A3 and SLC2A4 were significantly lower in breast invasive carcinoma than in pairing normal tissues." (PMID 34525987, 2021).
breast tumors (1 paper, 2023). "Specifically, SLC2A1, SLC2A6, SLC2A10, and SLC2A13 were significantly overexpressed, whereas SLC2A3, SLC2A4, SLC2A9, SLC2A11, and SLC2A12 had downregulated expressions in breast tumors compared with those in normal breast epithelium." (PMID 37108300, 2023).
CADASIL (1 paper, 2020). "To shed light on the mechanism of previously observed lower FDG-PET value in the CADASIL subjects, we investigated gene expression levels of GLUT isoforms [SLC2A2 (GLUT2), SLC2A3 (GLUT3), and SLC2A4 (GLUT4)] in VSMC models of CADASIL and control subjects." (PMID 33101365, 2020).
dental caries (1 paper, 2019). The decay of a tooth, in which it becomes softened, discolored, and/or porous. "Effects of several previously reported genetic variants on taste and diet preference were confirmed and a previously unreported association between allelic variation in SLC2A4 and dental caries was identified." (PMID 31261961, 2019).
Hereditary factor I deficiency disease (1 paper, 2021). "The smallest group includes only one term (Translocation of SLC2A4 (GLUT4) to the plasma membrane), while Hereditary factor I deficiency disease, as the largest group, includes 29 terms." (PMID 34027422, 2021).
lymphoma (1 paper, 2017). A malignant (clonal) proliferation of B- lymphocytes or T- lymphocytes which involves the lymph nodes, bone marrow and/or extranodal sites. "Altered expressions of SLC2A family members have been reported in many types of cancer (liver- SLC2A1, SLC2A2, SLC2A5; pancreas- SLC2A1; breast- SLC2A1, SLC2A2, SLC2A4; stomach- SLC2A2, SLC2A4, SLC2A5, SLC2A14; lymphoma- SLC2A5)." (PMID 28978124, 2017).
stable angina (1 paper, 2022). "For example, the unique targets for stable angina include CASP7 and SLC2A4, while the target for unstable angina is NCF1." (PMID 35140797, 2022).
triple-negative breast carcinoma (1 paper, 2021). An invasive breast carcinoma which is negative for expression of estrogen receptor (ER), progesterone receptor (PR), and human epidermal growth factor receptor 2 (HER2). "Compared with normal tissues, SLC2A4 were significantly reduced in luminal, HER2 positive and triple negative breast cancers (p = 1.19E-11;p = 2.43E-11;p = 6.70E-12, respectively)." (PMID 34488531, 2021).
tumor (93 papers, 2006 to 2025). "Differently from BRAF-like PTCs, RAS-like tumours show higher levels of the inducible transporter SLC2A4 (alias Glut4) and of its main regulator, the transcription factor SLC2A4RG, whose expression levels are positively correlated across tumour samples." (PMID 37198319, 2023). "The Slc2a family, consisting of the genes Slc2a3, Slc2a4, Slc2a5, Slc2a6 and Slc2a7, is responsible for glucose transporters, and exhibited increased transcription in WT type mice tumor compared to KO tumor." (PMID 34685767, 2021). "We further searched potential regulated genes to seek the regulation function of SLC2A4 in tumorigenesis and tumor progression." (PMID 34488531, 2021). "Further, secreted HDGF promotes tumor angiogenesis, while nuclear HDGF activates glycolysis-related proteins, including enolase 2 (ENO2) and solute carrier family 2 member 4 (GLUT4), followed by an increase in glycolysis to cause tumor growth in GC." (PMID 32429972, 2020). "Both glucose uptake and the expression of the glucose transporter Glut1 (Slc2a1), but not that of Glut2 (Slc2a2), Glut3 (Slc2a3), or Glut4 (Slc2a4), were elevated in Cpt1a-deficient ErbB2 tumor cells." (PMID 39097623, 2024). "There was a substantial overlap within gene expression profiles after in silico treatment of tumor cell lines with cardiotonic molecules, and only one gene specifically induced by BD-8 (Slc2a4, member of the solute carrier family 2–facilitated glucose transporter)." (PMID 39329752, 2024). "Among these, SLC26A10 and SLC2A4 showed log2FC ≤ −4 in 11 and 8 tumor types, respectively." (PMID 37397501, 2023). "Finally, the generated anticancer putative AMPs were used in this study to inhibits Slc2a4; an important protein that responsible for energy productions during angiogenesis in tumour formation and this can serve as another novel therapeutic agent for the treatment and management of cancer." (PMID 29382080, 2018). "LUAD tumor tissues showed higher mRNA expressions of SLC2A1, SLC2A5, and SLC2A12 and lower expressions of SLC2A3, SLC2A4, SLC2A6, SLC2A9, and SLC2A14." (PMID 36518662, 2022). "Hsa-miR-223-3p targets the EPB41L3, a potential tumor suppressor gene, the NFIX gene that regulates both cell proliferation and migration, the SLC2A4/GLUT4 is a glucose transporter and a biomarker for many types of malignant tumors." (PMID 31540229, 2019). "In cancers, where a sustained energy supply and lipogenic signaling are essential for tumor growth and survival, DHA-induced restriction of energy influx, together with the downregulation of Pparγ, Fabp4, Fasn, Gpr120, and Slc2a4, disrupts key pro-tumorigenic pathways." (PMID 41373668, 2025). "Mechanistically, m6A modification enhanced the expression of hepatoma-derived growth factor (HDGF), which could activate solute carrier family 2 member 4 (GLUT4) and enolase 2 (ENO2) to potentiate aerobic glycolysis in tumor cells." (PMID 33879256, 2021). "Glucose transporters include SLC2A1, SLC2A2, SLC2A3, and SLC2A4, and we found the expression of SLC2A1 was significantly upregulated in HCC tumor, contrast with that in adjacent non-tumor tissues (from TCGA Database)." (PMID 37443106, 2023).
cancer (80 papers, 2006 to 2025). A tumor composed of atypical neoplastic, often pleomorphic cells that invade other tissues. "Emerging evidence suggests that pharmacological inhibition of Solute carrier family-2-member-4-gene (Slc2a4), which encodes glucose transporter 4 protein (GLUT4), is an attractive therapeutic target for the development of a novel drug candidate for the treatment of cancer." (PMID 29382080, 2018). "As for solute carrier family-2-member-4-gene (SLC2A4), encoding glucose transporter-4-protein (GLUT4), it has been reported to serve as a novel therapeutic candidate for cancer treatment." (PMID 36866237, 2023). "In this study, we systematically explore the mRNA expression, prognostic value, epigenetic and genetic alterations, and gene regulatory network of SLC2A4 in human cancers." (PMID 34488531, 2021). "It has been shown that SLC2A4 expression is elevated during cancer progression, 23], consistent with our results." (PMID 33435953, 2021). "We found that mRNA expression of SLC2A4 was significantly downregulated in all individual cancer stages (p < 0.01)." (PMID 34488531, 2021). "In contrast, PPP2R2A was the most deleted gene found in > 20% of samples across 17 cancers, followed by the deletion of SLC2A4 in 16 cancers and five additional genes (FOXO3, PPP2CB, PPP2R2D, PPP2R5C and PPP2R5E) in 15 cancer types." (PMID 32807122, 2020). "Solute carrier family-2-member-4-gene (Slc2a4) which encodes glucose transporter 4 protein (GLUT4), has been identified as a promising therapeutic target for cancer." (PMID 29382080, 2018). "This study using in silico approach sought to identify potential plant antimicrobial peptides as selective inhibitors of Slc2a4 in order to develop a more potent anti-cancer therapy with high efficacy, excellent tolerability, and few transient side effects." (PMID 29382080, 2018). "Slc2a4 can serve as a potential biomarker for diverse kinds of malignant tumours such as; breast cancer, lung carcinoma, gastric cancer, and endometrial carcinoma." (PMID 29382080, 2018). "Altogether, the results reported in this study can usefully be employed for the rational design of novel, selective and potent Slc2a4 inhibitors in the search for novel anti-cancer therapy with high efficacy." (PMID 29382080, 2018). "Solute carrier family-2-member-4-gene (Slc2a4) encodes GLUT4, which functions as an insulin-regulated facilitative glucose transporter and has been identified as a promising therapeutic target for cancer." (PMID 35711425, 2022). "Besides, 7 antimicrobial peptides (RAB1-7) became anti-cancerdrugs by inhibiting SLC2A4 to impair the energy gained by cancer cells during angiogenesis." (PMID 34488531, 2021). "In conclusion, these results provide insight into SLC2s in human cancers and suggest that SLC2A4 could be an unfavorable prognostic biomarker for the survival of BRCA patients." (PMID 34488531, 2021). "Hence, this study reveals that all the generated AMPs can serve as therapeutic drug in treating cancer by inhibiting Slc2a4 which is responsible for the production of energy for cancer cells during angiogenesis." (PMID 29382080, 2018). "This is the first report on AMPs as inhibitors of Slc2a4 for the treatment of cancer." (PMID 29382080, 2018). "Numerous research studies have hypothesis several ways in which Slc2a4 results in cancer progression and metastasis one of which is the regulation of TRIM24–DDX58 axis that promote head and neck cancer (HNCC) metastasis." (PMID 29382080, 2018). "Additionally, SLC2A4 can also abnormally express in other types of cancers." (PMID 34488531, 2021). "From our best research, HOXC6, SLC2A4, VIP, CD1A, STC2, and OLFM2 are related to cancer progression." (PMID 35711425, 2022). "ASPSCR1 (↑2.6X twins), is a UBX domain containing tether for SLC2A4, which has a known fusion protein to TFE3 that is involved in certain cancers." (PMID 33115496, 2020).
cancer (continued). "Another important pathway related to SLC2A4 was AMP-activated proteinkinase (AMPK) pathway, which was a highly conserved and widely expressed energy balance regulator in eukaryotic cells and play a key role in carcinogenesis and cancer drug resistance." (PMID 34488531, 2021). "In this study, Slc2a4 protein sequence was retrieved and analysed using in silico approaches, and we identified seven putative antimicrobial peptides (AMPs; RAB1-RAB7) as anti-cancer." (PMID 29382080, 2018). "Although, the exact mode of action between Slc2a4 and cancer formation, progression and metastasis as not been fully understood." (PMID 29382080, 2018). "Analyzing protein–protein interaction network in STRING database, SLC2A4 also participates in the translocation of SLC2A4 (GLUT4) to the plasma membrane and protein localization to plasma membrane through enriched proteins such as EXOC5 and C2CD5, which play an important role in human cancers." (PMID 34488531, 2021).
metabolic disorders (44 papers, 2010 to 2025). "Castration further leads to glycolipid metabolic disorders and increased expression of inflammatory cytokines by affecting the expression of HSD11B1, SGK1, PCK1, and SLC2A4 in abdominal adipose tissues and their regulatory factors." (PMID 35456474, 2022).
infection (24 papers, 2012 to 2025). The state of being infected such as from the introduction of a foreign agent such as serum, vaccine, antigenic substance or organism. "AMPK activation led to the reversion of Ppargc1a and Slc2a4 transcription and consequently to increase infection burdens." (PMID 25738568, 2015).
SLC2A4 also shares sentences with these, for which no sentence is quoted: Glucose intolerance (96 papers); type 1 diabetes (21); heart failure (20); Hypertension (20); diabetic cardiomyopathy (19); Impaired glucose tolerance (19); ischemia (16); polycystic ovary syndrome (16); hyperlipidemia (14); Hepatic steatosis (11); Cognitive impairment (10); pancreatic cancer (10); HCMV infection (9); multiple myeloma (8); cardiomyopathy (7); diabetic nephropathy (7); glucose metabolism disorder (7); myocardial ischemia (7); endothelial dysfunction (6); ovarian carcinoma (6); sarcopenia (6); cardiovascular disease (5); cervical carcinoma (5); colon cancer (5); depression (5); hepatocellular carcinoma (5); memory impairment (5); myopathy (5); non-alcoholic fatty liver disease (5); Alzheimer disease (4).
A further 155 diseases each share a sentence with SLC2A4 in 4 papers or fewer.